CXCR2 (C-X-C motif chemokine receptor 2)
Diseases named in the same sentence as CXCR2 in open-access papers (continued):
Sharing a sentence is not in itself a finding about the gene and the disease.
bacterial sepsis (3 papers, 2014 to 2022). "Here, we provide evidence that Mincle promotes neutrophil recruitment by increasing CXCR2 surface expression in response to injury resulting from bacterial sepsis." (PMID 28112221, 2017). "We show here a novel function of fibrates in exerting protective effects during bacterial sepsis by promoting neutrophil recruitment and efficient early clearance of pathogenic bacteria at the site of infection which could be traced back to fibrate-mediated stabilization of CXCR2 expression." (PMID 24755316, 2014). "Although this correlation is believed to be due to increased internalization of CXCR2, our data suggest that a lack of increased expression of the receptor during bacterial sepsis may also be transcriptionally regulated, however this notion requires further investigation." (PMID 36054235, 2022).
Cerebral ischemia (3 papers, 2013 to 2021). Restriction of arterial blood supply to the brain associated with insufficient oxygenation to support the metabolic requirements of the tissue. "Inhibiting both CXCR1 and CXCR2 decreased polymorphonuclear lymphocyte infiltration and improved neurological function in permanent and transient rat cerebral ischemia." (PMID 24662979, 2014). "The release of CXCR2-positive granulocytes in bone marrow at the early stage of cerebral ischemia (4 hours) is related to the rapid systemic up-regulation of CXCL1 (CXCR2 ligand) and granulocyte colony-stimulating factor (key cytokines involved in bone marrow leukocyte mobilization)." (PMID 34335600, 2021). "CXCR2 blockade resulted in reduced mobilization of granulocytes from the bone marrow, caused an unexpected increase in circulating granulocytes, but failed to affect brain injury induced by cerebral ischemia." (PMID 24478617, 2013). "Granulocyte responses to cranial injury or cerebral ischemia involve primarily the mobilization of CXCR2-positive granulocytes, which is not seen after manipulation of extracranial tissues." (PMID 24478617, 2013).
chronic myeloid leukemia (3 papers, 2023 to 2025). "CXCR2 antagonism has been shown to decrease c-Myc expression in bone marrow of patients with chronic myeloid leukemia, through a CXCR2-mTOR-c-Myc cascade." (PMID 38481391, 2023).
chronic pancreatitis (3 papers, 2015 to 2024). A chronic inflammatory process causing damage and fibrosis of the pancreatic parenchyma. "Taken together, our data show that loss of CXCR2 reduces the number of infiltrating innate immune cells in chronic pancreatitis, thus protecting the pancreatic parenchyma from destruction by neutrophils and macrophages." (PMID 25950520, 2015). "Thus, CXCR2 is critically involved in the development of acute and chronic pancreatitis in mice, and its inhibition or loss protects against pancreatic damage." (PMID 25950520, 2015). "The clear association between CXCR2‐positive cells and acinar collapse observed in human chronic pancreatitis suggests that CXCR2 may be a powerful therapeutic target in these patients." (PMID 25950520, 2015). "Furthermore, we have shown that CXCR2 signalling links the progression of persistent acute inflammation to changes associated with chronic pancreatitis." (PMID 25950520, 2015). "Worth noting are also the results of the study of the CXCR2 Ligands/CXCR2 biological axis in the blood, tissue, and cystic fluid samples from healthy individuals, as well as in those with chronic pancreatitis, and PC (NCT00851955)." (PMID 39020414, 2024). "tested the therapeutic potential of CXCR2 inhibition in the prevention and treatment of chronic pancreatitis." (PMID 36969002, 2023). "They used CXCR2-inhibiting peptidase in a wild-type mouse model of chronic pancreatitis for full treatment." (PMID 36969002, 2023). "Neutrophil depletion was less effective in this model, suggesting that CXCR2 on non‐neutrophils contributes to the development of chronic pancreatitis." (PMID 25950520, 2015). "Next, we tested the therapeutic potential of CXCR2 inhibition in the prevention and treatment of chronic pancreatitis." (PMID 25950520, 2015). "The chemokine receptor CXCR2 drives neutrophil recruitment during inflammation, and to investigate its role in pancreatic inflammation, we induced acute and chronic pancreatitis in wild‐type and Cxcr2−/− mice." (PMID 25950520, 2015). "When we examined expression of CXCR2 in tissue from patients with chronic pancreatitis, we found that while a substantial proportion of the pancreas had been replaced by fibrotic tissue, dying acini were heavily infiltrated with CXCR2‐positive cells." (PMID 25950520, 2015). "CXCR2 knockout protected against atrophic changes within the pancreas when chronic pancreatitis was induced." (PMID 25950520, 2015). "We demonstrated the ability of CXCR2 inhibition to interfere in the necrotic process of acute pancreatitis, suggesting the potential for therapeutic trial in both acute and chronic pancreatitis." (PMID 25950520, 2015). "Here, using genetically modified mice, we show that CXCR2 is critical for the recruitment of neutrophils into the pancreas in models of acute and chronic pancreatitis, and that this plays a key role in driving the acinar cell damage seen in these models." (PMID 25950520, 2015). "To investigate whether CXCR2 might play a role in this process, we wanted to examine the role of CXCR2 in a mouse model of chronic pancreatitis." (PMID 25950520, 2015). "Furthermore, CXCR2 deletion protected against atrophic changes within the pancreas when chronic pancreatitis was induced." (PMID 25950520, 2015). "By extension of our studies from acute pancreatitis, through recurrent acute inflammation, to the changes of chronic pancreatitis, we have demonstrated the importance of CXCR2‐mediated immune cell infiltration to the propagation of all stages of pancreatic inflammation." (PMID 25950520, 2015). "Moreover, a CXCR2 inhibiting peptide, ‘pepducin’, protects wild‐type mice against acute and chronic pancreatitis and, significantly, can reverse established pancreatic inflammation." (PMID 25950520, 2015). "Thus, inhibitors of CXCR2 signalling could be of benefit in the treatment of both acute and chronic pancreatitis in humans." (PMID 25950520, 2015).
Clear Cell Renal Cell Carcinoma (3 papers, 2016 to 2020). "High expression levels of CXCR2 or CXCR3 were found to be associated with patients with advanced stage renal clear cell carcinoma." (PMID 27297979, 2016). "High expression levels of CXCR2 or CXCR3 were found to be significantly associated with the high‐risk group of patients with renal clear cell carcinoma." (PMID 27297979, 2016).
deep vein thrombosis (3 papers, 2022 to 2024). "Furthermore, in a mouse model, P-selectin in neutrophils activated the synergistic effects of PSGL-1 and C-X-C motif chemokine receptor 2 (CXCR2), thereby promoting neutrophil adhesion in blood flow-restricted veins, stimulating the release of NETs, and ultimately leading to deep vein thrombosis." (PMID 37680629, 2023).
diabetic kidney disease (3 papers, 2021 to 2025). Progressive kidney disorder caused by vascular damage to the glomerular capillaries, in patients with diabetes mellitus. "The results implied that CXCL1/CXCR2 mediated inflammation may play a vital role in the occurrence and development of diabetic nephropathy." (PMID 34975537, 2021). "Interestingly, preclinical data suggest that the use of Ladarixin, a non-competitive, dual allosteric inhibitor of CXCL8 (IL-8) receptors (CXCR1 and CXCR2), may reduce the burden of diabetic kidney disease as the IL-8-CXCR1/2 axis contributes to diabetic kidney disease." (PMID 40215252, 2025).
endometriosis (3 papers, 2007 to 2025). The growth of functional endometrial tissue in anatomic sites outside the uterine body. "Neutrophil-associated gene expression in endometriosis lesions decreased with α-CXCR2 treatment." (PMID 39836475, 2025). "Important for neutrophil recruitment is CXCR2 and its associated factors that are implicated in the initiation of endometriosis; thus, they are becoming a pathway of interest for determining how neutrophils promote inflammatory conditions driving endometriosis." (PMID 39836475, 2025). "In contrast, the ratio of aged neutrophils (CD45+CD66b+CD193–CD16–CXCR2+) (expressing CXCR2) to total neutrophils (CD45+CD66b+CD193–) increased significantly by 2-fold in endometriosis compared with control." (PMID 39836475, 2025). "Increased neutrophils in the PF of women with endometriosis and in vivo mouse studies of inflammatory diseases strongly suggest a role for CXCR2 and its ligands in endometriosis development." (PMID 39836475, 2025). "Moreover, in patients with endometriosis, CXCR2 is increased in endometrial biopsies shown by microarray and IHC analyses implicating it in the inflammatory profile of endometriosis." (PMID 39836475, 2025). "α-CXCR2 treatment reduces neutrophil recruitment into PF and endometriosis lesions." (PMID 39836475, 2025). "Minced endometrial tissue pieces from donor mice were dispersed via surgical incision and injection into the peritoneum of GFP– host mice, and treated with IgG or α-CXCR2 (2.5 mg/kg in 1× PBS, bidiurnally) with pretreatment beginning 6 days prior to endometriosis induction." (PMID 39836475, 2025). "Furthermore, glandular epithelial cell localisation and upregulation of immunoreactive CXCR1 and CXCR2, which bind CXCL8, has been demonstrated in eutopic and ectopic tissue sections from endometriosis patients when compared to controls." (PMID 17506907, 2007). "Thus, given these low levels of expression, Cxcr2 expression in IgG-treated minced endometrial tissue was normalized relative to ribosomal RpL7 gene expression to enable comparisons between treatment and endometriosis groups." (PMID 39836475, 2025).
endotoxemia (3 papers, 2016 to 2024). "Furthermore, CXCR2-specific antibodies prevented the release of BM neutrophils in both Cmtm3 WT mice and Cmtm3 KO mice in the LPS-induced endotoxemia model, as shown in." (PMID 39455728, 2024). "Besides, p38 is involved in the down-regulation of neutrophil CXCR1 and CXCR2 during human endotoxemia but the detailed mechanism remains to be discovered." (PMID 27655676, 2016). "In lipopolysaccharide (LPS)-induced endotoxemia, METTL3 controls neutrophil release from the bone marrow into the circulation in a TLR4-signaling-dependent mechanism involving surface expression of CXC chemokine receptor 2 (CXCR2)." (PMID 39686999, 2024).
gastric tumor (3 papers, 2013 to 2020). "The current study found that stimulation of PADI4 increased CXCR2, KRT14 and TNF-α expression levels, suggesting that increased expression of PADI4 in gastric tumor tissues, as we previously observed, contributes to tumorigenesis by increasing the expression levels of CXCR2, KRT14 and TNF-α." (PMID 27556695, 2016). "To confirm the universality of these expression changes, we measured the levels of CXCR2, KRT14 and TNF-α in SGC 7901 cells, which are also derived from gastric tumors." (PMID 27556695, 2016).
head and neck squamous cell carcinoma (3 papers, 2012 to 2024). A squamous cell carcinoma that arises from any of the following anatomic sites: lip and oral cavity, nasal cavity, paranasal sinuses, pharynx, larynx, and salivary glands. "IL-8 (CXCL-8) is a member of the CXC chemokines family and IL-8 receptors CXCR1 and CXCR2 are expressed on various normal and cancerous cells including head and neck squamous cell carcinoma." (PMID 22507529, 2012).
Hepatic steatosis (3 papers, 2013 to 2024). Steatosis is a term used to denote lipid accumulation within hepatocytes. "Ibuprofen treatment was also validated to downregulate CXCR1 and CXCR2 in peripheral blood mononuclear cells (PBMCs) and improve glucose tolerance, hypertriglyceridemia, hepatic steatosis, and liver inflammation in lipodystrophy mice." (PMID 38989000, 2024). "ALT, AST, and AST/ALT ratio all contributed to liver abnormalities that contained fatty liver, liver calcification, and liver cysts, IL-8 and CXCR2 correlated with each other strongly and showed significant associations with oxidative stress markers, even AST/ALT ratio." (PMID 39108287, 2024).
keratitis (3 papers, 2019 to 2022). A corneal disease that is characterized by inflammation of the cornea. "The chemokine receptor 2 (CXCR2) has also been implicated as a facilitator of the inflammatory response during S. aureus keratitis." (PMID 31703354, 2019). "The authors concluded that the infiltration of PMNs into the corneal epithelium during P. aeruginosa and S. aureus keratitis was highly dependent on IL-8 activating CXCR2, which therefore upregulated adhesion molecules that are needed for PMN infiltration." (PMID 31703354, 2019).
laryngeal squamous cell carcinoma (3 papers, 2015 to 2022). A squamous cell carcinoma that arises from the larynx. "In our previous research, high expression of CXCR2 was detected in human laryngeal squamous cell carcinoma and was significantly associated with its poor prognosis." (PMID 25944970, 2015).
lung squamous cell carcinoma (3 papers, 2021 to 2024). "The chemokine receptor CXCR2 has also been shown to be elevated in the stroma and tumor cells of adenocarcinomas and squamous cell carcinomas of the lung, and its overexpression was associated with shorter survival." (PMID 39639338, 2024).
metastasis (3 papers, 2017 to 2025). The spread or migration of cancer cells from one part of the body (where they first appeared) to another. "CXCL1 expression in cancer cells was significantly correlated significantly with T invasion (T2–T4), lymph node metastasis, lymphatic invasion, venous invasion, peritoneal cytology, peritoneal metastasis, and CXCR2 expression in stromal cells." (PMID 28575019, 2017).
myeloma (3 papers, 2014 to 2025). "Certainly we were able to observe that SDF-1, which binds to CXCR4, and CXCL8 (IL-8) which is a ligand for CXCR1/CXCR2, are also significantly elevated in myeloma." (PMID 28389623, 2017). "The article examines the role of CXCR1, CXCR2, and CXCR3 ligands in tumor biology in multiple myeloma (MM) and monoclonal gammopathy of undetermined significance (MGUS)." (PMID 40940985, 2025).
papillary thyroid carcinoma (3 papers, 2021 to 2022). "By upregulating β‐catenin signalling pathway, CXCR2 increased migration, invasion and epithelial–mesenchymal transition of the papillary thyroid carcinoma cells." (PMID 36349481, 2022). "It is well established that the CXCL5/CXCR2 and IL-8/CXCR1/CXCR2 axes contribute to carcinogenesis by promoting tumor cell proliferation, migration, and invasion, and the EMT process of many tumor cells, including NSCLC, hepatocarcinoma cells, and papillary thyroid carcinoma cells." (PMID 34822613, 2021).
peripheral arterial disease (3 papers, 2022 to 2025). A disorder of the arteries supplying the upper and lower extremity and the visceral organs. "The pathways associated with neutrophil activation, chemotaxis, and migration were significantly correlated with the high expression of S100A8, S100A9, S100A12, and CXCR2 in CD and peripheral arterial disease." (PMID 40422241, 2025). "This bioinformatic study elucidates S100A8, S100A9, S100A12 and CXCR2 as hub genes for the co-occurrence of Crohn’s disease and peripheral artery disease." (PMID 35795659, 2022). "Based on the results from selecting hub genes among 15 potential candidate genes, four hub genes were selected that were significantly upregulated in both CD and peripheral arterial disease: S100A8, S100A9, S100A12, and CXCR2." (PMID 40422241, 2025).
pneumococcal pneumonia (3 papers, 2011 to 2023). A febrile disease caused by STREPTOCOCCUS PNEUMONIAE. "On the other hand, another study showed that pretreatment with SB-225002, a CXCR2 antagonist, increased bacteria burden and showed that CXCR2 was essential to protect mice from pneumococcal pneumonia." (PMID 29326698, 2017). "The engagement of CXCR2 by CXC chemokines is critical for neutrophil recruitment in murine models of pneumococcal pneumonia." (PMID 21298030, 2011).
pneumonitis (3 papers, 2019 to 2025). An inflammatory process affecting the lung parenchyma. "For example, neutrophils from pneumonitis and peritonitis (as well as healthy and arthritic blood) exhibited a predominance of Cxcr2, encoding the receptor for key neutrophil recruitment chemokines KC (CXCL1) and MIP2 (CXCL2)." (PMID 34001893, 2021). "The study found that elevated levels of C-X-C chemokine receptor type 2 (CXCR2), IL-1 receptor antagonists, and IL-2 receptor antagonists were associated with the onset and progression of pneumonitis, suggesting a potential link between these immune markers and treatment-induced lung inflammation." (PMID 40299683, 2025). "Circulating biomarker analyses demonstrated increases in CXCR2, IL1ra and IL2ra that coincided with the development of symptomatic pneumonitis." (PMID 31014385, 2019).
pyelonephritis (3 papers, 2009 to 2025). An inflammatory process affecting the kidney. "In addition, reduced expression levels of CXCR1 and CXCR2 on neutrophils was associated with pyelonephritis and recurrent cystitis, respectively." (PMID 20016852, 2009). "The chemokine receptors CXCR1 and CXCR2, highly expressed on neutrophil surfaces, enable their recruitment to kidney infection sites by CXCL1 and CXCL." (PMID 40308964, 2025). "Additionally, CXCR2 knockout mice have a higher chance of developing pyelonephritis, renal abscesses, and renal scarring when infected with UPEC, potentially leading to sepsis." (PMID 40308964, 2025). "In this study, we examined whether CXCR1, CXCR2, and TLR pathway polymorphisms are associated with ASB, urinary chemokines, and neutrophils in a cross-sectional study of adult women ages 18–49 years with and without a history of recurrent cystitis or pyelonephritis." (PMID 20016852, 2009).
renal fibrosis (3 papers, 2023 to 2026). A final common manifestation of a wide variety of chronic kidney diseases characterized by glomerulosclerosis and tubulointerstitial fibrosis. "A single-cell analysis pointed out that CXCL1 is secreted from pro-fibrotic tubules and then recruits CXCR2 + basophils, which is a key factor in renal fibrosis." (PMID 40078458, 2025). "In our study, Ang II infusion markedly increased the levels of chemokines (CXCL1 and GCSF) and CXCR2 (the receptor of CXCL1) in the kidney, and Dectin-1 deficiency attenuated Ang II-induced renal dysfunction and renal fibrosis." (PMID 37340199, 2023).
septic shock (3 papers, 2018 to 2023). Shock caused by infection; frequently caused by gram negative bacteria, although some cases have been caused by other bacteria, viruses, fungi, and protozoa; characterized by fever, chills, tachycardia, tachypnea, and hypotension. "The surface expression of the chemokine (C-X-C motif) receptor 2 (CXCR2) and adhesion molecule CD11b have also been found to be reduced on neutrophils isolated from patients with septic shock compared with healthy controls." (PMID 30300408, 2018). "Also, the multilevel regression analysis assessing associations between the measurements of neutrophil functions and SOFA score found that, after adjusting for the effect of time, the percentages of CXCR2-negative neutrophils could predict SOFA score in patients with septic shock (p = 0.001)." (PMID 33424860, 2020).